BCL2 (BCL2 apoptosis regulator)
Diseases named in the same sentence as BCL2 in open-access papers (continued):
Sharing a sentence is not in itself a finding about the gene and the disease.
melanoma (continued). "CDK4/6 inhibition in melanoma cells resulted in apoptosis associated with deregulation of BCL2, BCL2L1, BIRC5 and BIM." (PMID 30349650, 2018). "Disruption of Mitf in melanocyte or melanoma triggers profound apoptosis and is susceptible to rescue by B-cell lymphoma 2 (BCL2) overexpression." (PMID 30544544, 2018). "As Bcl-2 protein plays a relevant role in melanoma, being associated with melanoma progression, resistance to apoptosis and poor prognosis, we investigated the effect of Bcl-2 modulation on Sema5A expression." (PMID 30454024, 2018). "We have also shown that Bcl-2 regulates the activity of transcription factors, such as microphthalmia-associated transcription factor, a master regulator of melanocyte and melanoma biology, and consequently its specific target genes, TRPM1, MLANA and miR-211." (PMID 30454024, 2018). "It has been shown that I3C promoted apoptosis in UVB-sensitized melanoma cells through the inhibition of Bcl-2 expression and down-regulation of microphthalmia-associated transcription factor (MITF)." (PMID 29565284, 2018). "We also focused on the functional relation between Sema5A and Bcl-2, an anti-apoptotic protein associated with melanoma progression, resistance to apoptosis and poor prognosis." (PMID 30454024, 2018). "The expression of miR-181a was promoted by piceatannol and it caused up-regulation of Bax, down-regulation of Bcl-2 and activation of caspase-3, ultimately induced the apoptosis in melanoma cells." (PMID 29041990, 2017). "Highly expressed level of Bcl-2 has been reported in various cancers including melanoma, and has been broadly linked to its anti-apoptotic activity in melanoma cells, silencing by miRNAs." (PMID 29041990, 2017). "An obviously inverse association was confirmed between miR-219-5p level and Bcl-2 protein level in melanoma tissues." (PMID 28884131, 2017). "Sirt1 stable silencing increased Mxd1 mRNA expression and led to down-regulation of MYC targets, such as Cdkn1a, Bcl2 and Psen2, whose upregulation is associated with human melanoma aggressiveness and poor prognosis." (PMID 29383100, 2017). "High expression of Bcl-2, an anti-apoptotic factor, has been associated with resistance to chemotherapy in human melanoma and other tumor types." (PMID 27941650, 2016). "In melanoma cells, besides cell cycle arrest, loss of Brn3a was associated with apoptosis and with decreased Bcl-2 and Bcl-xL levels." (PMID 23666755, 2013). "Treatment of human melanoma mouse xenografts with dinaciclib led to tumor regression associated with reduced retinoblastoma protein phosphorylation and Bcl-2 expression." (PMID 23527225, 2013). "The loss of the Bcl-2 expression during progression from primary to metastatic melanoma in patients suggests an active immune selection of the respective melanoma clones by the tumor bearing host, e.g. via a specific immune response." (PMID 21304176, 2010). "We also investigated the role of perforin and granzyme-B in the augmentation of 1H3-cell cytotoxicity against A02 melanoma cells associated with coexposure to the ABT-737 Bcl-2 inhibitor." (PMID 17311012, 2007). "Additionally, in melanoma tissues, high expression of Bcl-2 was associated with poor prognosis in patients." (PMID 40497999, 2025). "Moreover, the algorithm revealed that the expression of BCL-2 in the melanoma-infiltrating lymphocytes constitutes an important risk marker to predict metastasis." (PMID 37046835, 2023).
melanoma (continued). "On the other hand, it is of note that rampant genetic changes in melanoma are capable of reducing apoptosis through the overexpression of B-cell lymphoma 2 (Bcl-2), loss of both Phosphatase and tensin homolog (PTEN) and nuclear factor-κB (NF-κB), and mutation of Akt3, NRAS, and BRAF." (PMID 36224606, 2022). "Targeting nodes of the CD133, AKT, or BCL-2 survival pathways with trametinib highlights the potential for combination therapies for NRAS-mutant melanoma stem cells for the development of more effective treatments for patients with high-risk melanoma." (PMID 35216449, 2022). "It was also shown that following hypoxia exposure, melanoma cells bearing BRAF V600E mutation exhibit downregulation in the expression of genes encoding apoptotic regulators—BAD (Bcl-2-associated agonist of cell death) and BCL2L1 (Bcl-2-like 1, also known as Bcl-X)." (PMID 33918883, 2021). "Studies in transgenic medaka have shown that expression of Xmrk is correlated with STAT5 activation and increased expression of microphthalmia-associated transcription factor (MITF), which upregulates B-cell lymphoma 2 (Bcl-2) and surviving, and is also associated with melanoma progression." (PMID 34067095, 2021). "Collectively, this study and a previous one2, also indicate that Bcl-2 is a regulator of miRNA biogenesis and function, and that it could affect in vitro melanoma progression-associated properties through its effect on miRNA expression." (PMID 32060259, 2020). "As compared with H1299 control cells and similar to melanoma cells, CM from H1299 cells overexpressing bcl-2 promoted M2 polarization of M-DM, associated with increased expression of M2 (CD206, IL-10 and CCL1) and reduction of M1 (COX-2 and IL-12) markers and increased THP-1 cell migration." (PMID 32269145, 2020). "In G6PD-deficient melanoma cells, the expression of Bcl-2 and Bcl-xL is significantly reduced." (PMID 31500396, 2019). "Likewise, a ratio of Bax/Bcl-2 was reported, in other research, as a regulator that determined the susceptibility to apoptosis in melanoma cells." (PMID 27807471, 2016). "Importantly, IL24 exposure induced apoptosis by reduction of pro-apoptotic Bcl2 proteins and caused a G2/M cell cycle arrest; a similar effect observed in melanoma cell lines treated with GSK126." (PMID 26304929, 2015). "In addition, increased expression of BCL-XL is associated with a poor prognosis in patients with melanoma and elevated BCL-2 and BCL-XL are associated with a poor response to chemotherapy." (PMID 24983357, 2014). "Additionally, our previous studies on tissue sections have shown that Mcl-1 and Bcl-XL expression is associated with progression of melanoma, whereas Bcl-2 levels decrease during progression of melanoma." (PMID 24367627, 2013). "In addition, loss of Bcl-2 expression in melanoma compared to benign nevi has been observed by others." (PMID 22292048, 2012). "Interestingly, BMP-induced apoptosis, similar to what has been described earlier for MSX2 over-expression in melanoma, has also been associated with a downregulation of BCL2 and Survivin." (PMID 21730974, 2011). "However, whether LNT affects melanoma cell apoptosis by regulating the association between Nur77 and Bcl-2 remains unknown." (PMID 39744474, 2025). "The combination of mebendazole and MEK inhibitor (trametinib) dramatically inhibited ERK1/2 phosphorylation, suppressed the ERK1/2‐mediated pathways, and decreased expression of BCL2 in NRASQ61K melanoma cell lines." (PMID 41492362, 2026). "MITF is the production of antiapoptotic Bcl‐2 gene, and it also related to the survival of melanocytes and melanoma cells." (PMID 41492362, 2026). "For example, BCLXL and MCL1 are critical for cell survival in melanoma, rendering them inherently resistant to BCL2 inhibitors alone." (PMID 41155156, 2025). "The inhibitors induced both melanoma cell apoptosis with downregulated Bcl-2 and upregulated cytochrome c proteins." (PMID 41403742, 2025).
melanoma (continued). "Additional investigations revealed a pro-apoptotic effect, evidenced by morphological changes in melanoma cells, showing the downregulation of anti-apoptotic Bcl-2 and upregulation of pro-apoptotic Bax." (PMID 40427124, 2025). "Summarizing that resveratrol in melanoma cells and downregulating the Erk/PKM2/BCl-2 axis seems to be a new method for preventing or treating melanoma." (PMID 40932870, 2025). "For example, the polyphenol curcumin has been shown to upregulate miR-205-5p in melanoma models, leading to tumor growth suppression via downregulation of Bcl-2 and PCNA." (PMID 40565936, 2025). "As a result, Bcl-2, an anti-apoptotic protein, is produced, supporting the survival of melanoma stem cells, and promoting tumour maintenance." (PMID 41463281, 2025). "Using a cell line stably knocked down for FKBP51, namely ShFKBP51.2, we confirmed the dependence on FKBP51 of melanoma BCL-2 expression levels." (PMID 40180895, 2025). "Taken together, our transcriptomic data show that melanoma cells treatment with recombinant RGD-apoptin leads to activation of apoptosis primarily via a Bcl-2-dependent mechanism." (PMID 41465443, 2025). "In oral, liver, and melanoma models, they induce apoptosis via Bax/Bcl-2 regulation, caspase activation, and suppression of cAMP-PKA-MITF and migration pathways." (PMID 41346617, 2025). "Further investigation was conducted to determine the mechanisms by which LNT exerts its anti-melanoma effects via Nur77 and Bcl-2 by assessing protein co-localization." (PMID 39744474, 2025). "Emodin exhibits pro-apoptotic effects in melanoma (B16-F10 and A375) cells by increasing the Bax/Bcl-2 ratio, and suppressing the Wnt/β-catenin pathway." (PMID 40490812, 2025). "RGD-Lip-SHK actively delivers more drugs to melanoma cells via αVβ3-mediated endocytosis and then induces apoptosis by regulating the expression of Bax and Bcl-2 proteins." (PMID 40496618, 2025). "As a result of the combination treatment, Bcl-2, an anti-apoptotic protein, decreased in both melanoma cell lines, while a significant increase was observed in pro-apoptotic Bax and pro-apoptotic caspase-9 and caspase-3 protein levels." (PMID 40063190, 2025). "In both melanoma cells, Bcl-2 protein levels were reduced by 3.6-fold and the levels of Bax, caspase-9, and caspase-3 were induced by 4.6-, 3.9-, and 4.3-fold in A375 cells, respectively." (PMID 40063190, 2025). "COP1, which inhibits ultraviolet-B stimulated growth in plants, suppresses nuclear ETS1 and ETS1-mediated expression of BCL2 in the murine melanomas and in human melanoma cells." (PMID 40562100, 2025). "Overall expression of Nur77 was decreased, whereas that of Bcl-2 was increased in melanoma cells after treatment with different doses of LNT." (PMID 39744474, 2025). "The researchers also employed Annexin V apoptosis assay and established that UA induces significant apoptosis in both tested melanoma cell lines, with a decrease in bcl-2 gene expression." (PMID 41465825, 2025). "Photodynamic therapy using the hybrid membrane-derived nano-formulation enhanced ROS levels and promoted early death of B16 melanoma cells via the Bax/Bcl-2 pathway." (PMID 40490812, 2025). "Small-interfering RNA-mediated Nur77 knockdown revealed that LNT promoted melanoma cell apoptosis via the Nur77/Bcl-2 pathway." (PMID 39744474, 2025). "Although the analysis of YAP target genes expression is recognized as a robust and quantifiable method to assess YAP activity, the level of YAP phosphorylation and nuclear translocation in melanoma cells overexpressing Bcl-2 was also assessed." (PMID 38755629, 2024).
melanoma (continued). "MITF target genes play important roles in melanoma survival, including inducing an increase in the expression of the antiapoptotic gene Bcl2, cell cycle-related gene CDK2, cell motility-related gene c-Met, and pigment production/secretion-related gene RAB27A." (PMID 39684511, 2024). "Firstly, we evaluated the ability of Bcl-2 overexpressing melanoma cells to affect in vitro ability of fibroblasts to migrate." (PMID 38755629, 2024). "Here, we characterized Bcl-2 functions to a deeper extent by extracting a specific signature by RNAseq analysis after Bcl-2 or Bcl-xL silencing in melanoma models." (PMID 38755629, 2024). "The cell-free extract of L. plantarum tested on high and low metastatic human malignant melanoma cells on a mice model induced intrinsic apoptosis by regulating Bax/Bcl-2 ratio." (PMID 39600571, 2024). "This inhibition leads to the downregulation of the antiapoptotic protein BCL-2, consequently reducing the viability of melanoma cells." (PMID 39203892, 2024). "NCT02836548 is a phase I/II ongoing clinical trial evaluating the efficacy and side effects of BCL-2 inhibitor Navitoclax in conjunction with dabrafenib and trametinib to target the apoptosis regulator BCL-2, which is typically overexpressed in melanoma." (PMID 39534873, 2024). "LHFPL3-AS1-long directly interacted with miR-181a-5p to prevent Bcl-2's mRNA from being degraded, inhibiting melanoma CSCs apoptosis." (PMID 39170516, 2024). "In melanoma cells, the depletion of these anti-apoptotic proteins, particularly Bcl-2, leads to cell death." (PMID 39594467, 2024). "This evidence was confirmed when A375 and M14 clones stably overexpressing Bcl-2 were plated on different stiffness gels: increased cell viability respect to control was observed when Bcl-2 overexpressing melanoma cells were plated in both 1 kPa and 50 kPa." (PMID 38755629, 2024). "Due to the important roles of intrinsic apoptosis pathways in melanoma cells, Bcl-2 proteins represent promising targets for melanoma therapy." (PMID 38542429, 2024). "We performed RNAseq analysis of siRNA-mediated transient knockdown of Bcl-2 or Bcl-xL in human melanoma cells and gene ontology analysis to identify a specific Bcl-2 transcriptional signature." (PMID 38755629, 2024). "The outcomes obtained from this study suggest that PHEC-66 triggers apoptosis in these melanoma cell lines by increasing the expression of pro-apoptotic markers (BAX mRNA) while concurrently reducing the expression of anti-apoptotic markers (Bcl-2 mRNA)." (PMID 38334660, 2024). "In melanoma cells, we also described the Bcl-2-mediated regulation of microRNA-211 and mitochondrial transcript levels through the interaction with SLIRP." (PMID 38755629, 2024). "In order to identify a Bcl-2 dependent transcriptome signature able to better discriminate between Bcl-2 and Bcl-xL functions, we performed RNAseq analysis of siRNA-mediated transient knockdown of Bcl-2 or Bcl-xL in human melanoma cells." (PMID 38755629, 2024). "It has also been revealed that curcumin showed antiproliferative and proapoptotic activity in melanoma cells via the BCL-2-mediated pathway." (PMID 39684513, 2024). "While the effects on ROS in response to the inhibitor combinations used here had not previously been investigated, some increase in ROS levels has been reported in melanoma cells in response to the Mcl-1/Bcl-xL/Bcl-2-selective BH3 mimetic TW-37." (PMID 38542429, 2024). "In order to assess the impact of Bcl-2 on the behaviour of melanoma cells in response to different mechanical properties of collagen, we used collagen-coated hydrogels plate." (PMID 38755629, 2024). "S2 human melanoma cells by inducing apoptosis through increasing the expression of apoptotic protein Bax and reducing the expression of anti-apoptotic protein Bcl-2 and also through the activation of caspase-9 and caspase-3." (PMID 39478959, 2024).
melanoma (continued). "Melanocytes and melanoma cells typically exhibit high levels of the anti-apoptotic caspase inhibitor Bcl-2, with impaired apoptosis being a crucial factor in cancer development." (PMID 39329914, 2024). "In accordance with previously published data, stable Bcl-2 overexpression induced a significant increase of in vitro cell migratory capacity of melanoma cells." (PMID 38755629, 2024). "Human foreskin fibroblasts, HFF, exposed for 24 h to CM derived from Bcl-2 overexpressing A375 and M14 clones showed higher capacity to migrate compared to fibroblasts exposed to CM derived from control melanoma cells, evaluated in a wound healing assay." (PMID 38755629, 2024). "The modulation of phenotypes as well as these proteins belonging to cadherin and BCL2 families via EBI3 has further completed the discovery highlighting the involvement of EBI3 in melanoma." (PMID 39726752, 2024). "In melanoma, high Bcl-2 expression is characteristic and correlates with apoptosis resistance, invasion, tumor growth, and metastasis." (PMID 38542429, 2024). "Rapamycin promotes autophagy in melanoma cells by blocking the mTOR pathway and increasing the protein levels of Bcl-2, Bax, and LC3-II." (PMID 39371094, 2024). "Downregulation of Mcl-1 or Bcl-2 in response to vemurafenib has also previously been reported in melanoma cells." (PMID 36902392, 2023). "Silencing of BCL2 in melanoma cells inhibits the polarization of M2 macrophages, promoting anti-cancer immunity and interfering with tumor progression." (PMID 37147395, 2023). "Our findings that LMW-F reduces Bcl-2 phosphorylation at Thr56 and downregulates Bcl-2 expression in melanoma cells are consistent with previous studies indicating that inhibiting Bcl-2 phosphorylation can overcome resistance mechanisms." (PMID 38186578, 2023). "Surprisingly, BCL-2 expression was detected here in both melanoma cells and in the tumor-infiltrating lymphocytes." (PMID 37046835, 2023). "Quercetin reduced the Bcl-2 expression as well as activity and enhanced the action and potential of caspase-3 within murine melanoma cells (B16-BL6) which led to the cells dying." (PMID 37803407, 2023). "To date, several transcription factors have been shown to control the activity of the BCL-2 promoter, for example, Aiolos in IL-2-deprived T cells, Mitf in the context of melanoma cell viability, and Pi in the context of B-cell differentiation." (PMID 38092733, 2023). "Molecular docking, confirmed through biological assessment, showed the significant affinity of all three esters for the anti-apoptotic Bcl2 protein, thus indicating their apoptotic anti-melanoma effects." (PMID 36615613, 2023). "Melanoma cells undergo apoptosis when Withaferin A is used alone due to its ability to down-regulate Bcl-2 and activate the formation of Reactive oxygen species (ROS)." (PMID 37803407, 2023). "The suppression of human A375 melanoma cells by ascorbate treatment and caspase-3 and caspase-9 activation, as well as induction of the Bcl-2- and Bax-mediated mitochondrial pathway, was already described by Chen and coworkers." (PMID 36672190, 2023). "Examinations revealed a pro-apoptotic effect, as evidenced by morphological changes in melanoma cells and supported by Western blot data showing the downregulation of anti-apoptotic Bcl-2 expression coupled with the upregulation of pro-apoptotic Bax." (PMID 37111343, 2023).